SOX2 (SRY-box transcription factor 2)
Diseases named in the same sentence as SOX2 in open-access papers (continued):
Sharing a sentence is not in itself a finding about the gene and the disease.
glioma (continued). "SOX2 is a pan glioma marker that has been shown to be the most pervasively expressed gene in high-grade gliomas." (PMID 34884748, 2021). "POU3F2 decreased upon SFRP2-overexpression and correlated positively to SOX2 expression in the CCLE glioma cell lines." (PMID 34021259, 2021). "Prrx1 expression was positively correlated with SOX2 positive rate in glioma tissues, with 76.1% and 37% in Prrx1-high and Prrx1-low groups, respectively." (PMID 34131109, 2021). "Our study provided evidence suggesting that collagen and FN collaborate to facilitate proliferation and tumorigenesis of glioma cells through the PI3K/AKT/SOX2 and CDC42/F-actin/YAP-1/Nupr1/Nestin pro-survival signaling networks." (PMID 33408794, 2021). "Our experimental findings of SFRP2 and SOX2 signaling events represent a scenario whereby SFRP2 counteracts SOX2 function allowing glioma cell progression from a proneural towards a mesenchymal phenotype." (PMID 34021259, 2021). "Squamous cancers and gliomas selectively amplify enhancers located 3′ and 5′ to the SOX2 gene, respectively, exhibiting a spatial switch of cancer type-specific copy number amplifications." (PMID 34880227, 2021). "Knockdown of HDAC1 resulted in a significant decrease in the expression of glioma master transcription factors SOX2 and OLIG2, stem cell marker NESTIN, and the receptor tyrosine kinase epidermal growth factor receptor (EGFR)." (PMID 34494550, 2021). "We previously showed the SOX2 is a pervasively expressed marker of transformed glioma cells in GBM using scRNA-seq and immunohistochemistry." (PMID 33975634, 2021). "In comparison, we also analyzed copy number data of gliomas (combined LGG and GBM), another cancer type that is associated with SOX2 overexpression." (PMID 34880227, 2021). "SOX2 has been reported to play a pivotal role in developing drug resistance of glioma and its expression was correlated with the grade of malignancy and favored the maintenance of an undifferentiated state of cancer stem cells." (PMID 34012924, 2021). "MicroRNA-21 promotes migration and invasion of glioma cells via activation of Sox2 and β-catenin signaling." (PMID 34789252, 2021). "The experimental results showed that treatment with 8 μM WP1066 reduced the expression of stem cell‐related markers Oct4, Bmi1, and Sox2 in glioma cells after EMT." (PMID 33788424, 2021). "In this study, we dissected the influence of SRR2 on SOX2 expression in glioma cells and demonstrated that the deletion of this regulatory region significantly reduces SOX2 levels, and hence activity in these cancer cells." (PMID 33805518, 2021). "METTL3 expression promoted radioresistance in glioma by promoting glioblastoma stem cell maintenance through m6A-mediated stabilization of SOX2, and subsequent METTL3 knockdown resulted in increased radiosensitivity." (PMID 33669361, 2021). "Our results were consistent with studies showing SOX2 overexpression in gastric cancer, lung squamous cell carcinoma, gastrointestinal cancers, cervical cancer, gliomas, and pancreatic carcinoma." (PMID 34436030, 2021). "Here, we reveal distinct copy number profiles at the SOX2 locus between squamous cancers and gliomas, which corresponds to the distribution of lineage-specific potential regulatory elements." (PMID 34880227, 2021). "To characterize the impact of SRR2 enhancer in SOX2 expression on glioma cells, we performed ChIP assays in U87MG and T98G parental and U87MG oncosphere populations, studying the presence or absence of p27KIP1 in this region." (PMID 33805518, 2021). "Previous studies have shown that the m6A RNA methylase METTL3 promotes glioma progression by stabilizing the expression of SOX2, suggesting an important role of m6A modifications in glioma." (PMID 34803608, 2021). "In glial tumors, CD3+ T cell infiltration correlates inversely with the expression of SOX2, an embryonal stem cell marker commonly expressed by glial tumors." (PMID 34830753, 2021).
glioma (continued). "Together, these findings present SFRP2 as a SOX2-antagonist with the capacity to induce a mesenchymal subtype transition in glioma cells located in vascular tumor areas, highlighting its role in glioblastoma tumor evolution and intratumoral heterogeneity." (PMID 34021259, 2021). "We observed elevated expression of SOX2 in 3D collagen/FN cultured glioma cells, and blockade of PI3K/AKT suppressed this phenomenon." (PMID 33408794, 2021). "Our results showed that the PI3K/AKT/SOX2 axis is critical in glioma cell proliferation induced by collagen/FN." (PMID 33408794, 2021). "Patient-derived glioma cells were characterized by immunofluorescence using Nestin, a neural progenitor marker, SOX2, a marker for pluripotency and self-renewal, and astrocytic marker GFAP confirms cells of glial origin in the culture." (PMID 34489494, 2021). "We provided evidence that collagen/FN complex regulates glioma stemness via an integrin αvβ3-activated PI3K/AKT/SOX2 and CDC42/F-actin/YAP-1/Nupr1/Nestin signaling network." (PMID 33408794, 2021). "In summary, our results highlight the central role of SRR2 to maintain high levels of SOX2 expression, and hence malignant properties of glioma cells establishing the requirement for this regulatory region for SOX2-driven tumorigenic activities." (PMID 33805518, 2021). "In our study, we found that anticarin β inhibits clonal spheres forming in human glioma cells and reduces the expression of stemness-related markers, such as Nanog, Oct4, Sox2, CD133, STAT3, and CD44." (PMID 34408983, 2021). "In recent years, SOX2, as an important transcription factor for maintaining glioma stem cells, has been considered as a new target for active immunotherapy." (PMID 34630121, 2021). "We examined the SOX2 and Nestin expression in SOX2 or Nestin knockdown glioma cells cultured in the 3D collagen/FN system." (PMID 33408794, 2021). "STAT3 can induce the expression of Sox2 stimulating self-renewal capacity and stemness in glioma-derived CSCs." (PMID 34884812, 2021). "In glioma, SOX2 expression promotes stemness via downstream activation of TGFβ signaling, which also promotes GSC stemness by activating SOX4." (PMID 34012965, 2021). "In this study, we uncovered an abnormal expression of B7-H6 that was coexpressed with Sox2 in glioma tissue." (PMID 32322592, 2020). "In summary, we uncovered abnormal upregulation of B7-H6 expression in human glioma tissues which was coexpressed with Sox2." (PMID 32322592, 2020). "SRY (sex determining region Y)-box 2, also known as SOX2, is upregulated in pediatric high-grade glioma and amplified in pediatric cell lines." (PMID 33050158, 2020). "Immunofluorescent staining confirmed that CBP was highly expressed in nuclei of glioma cells expressing the GSC markers SOX2 and OLIG2 in primary human GBMs." (PMID 33124191, 2020). "More importantly, Olig2 protein is synergistic with Sox2, Pou3f2 and Sall2 and is a key transcription factor of glioma initiating cells." (PMID 32943100, 2020). "The importance of this high expression is highlighted by the co-expression of SH3KBP1 and SOX2 in glioma clinical samples." (PMID 33643898, 2020). "Supporting our notion was that the coexpression of B7-H6 with Sox2 was found in some areas within tumor cells in the glioma tumor tissues." (PMID 32322592, 2020). "SOX2-based reporter systems were previously used to demonstrate the CSC phenotype of SOX2-expressing subpopulations in glioma, breast, prostate, bladder or head and neck cancers, although this strategy remained unexplored in sarcomas." (PMID 32295077, 2020). "When human glioma stem cells were intracranially injected with TAT-Cx43266–283 into immunodeficient mice, there was reduced expression of the stemness markers nestin and Sox2 in human glioma cells at 7 days post-implantation." (PMID 31883012, 2020). "Here, we show that B7-H6 expression is abnormally upregulated in glioma tissue and that B7-H6 is coexpressed with stem cell marker Sox2." (PMID 32322592, 2020).
glioma (continued). "The Skp2 suppression delayed cell proliferation, sphere formation, and tumorigenesis, while the enhancement of Skp2 increased stem cell markers Nestin and Sox2 in glioma." (PMID 32165861, 2020). "SOX2 has been identified as a tumor-associated antigen in the patients with both LSCC and glioma, where SOX2-specific T cell immune responses are mounted against SOX2 and this phenomenon results in tumor regression." (PMID 30517668, 2020). "METTL3 promotes mRNA methylation and enhances the stability of SRY-box transcription factor 2 (SOX2), increases SOX2 protein expression, and promotes the maintenance and radiation resistance of glioma stem-like cells." (PMID 32398132, 2020). "CD133 accompanying with other neural and hematopoietic stem cell marker including Musashi-1, Nestin, Sox2, and Olig2 can identify glioma stem cells from different molecular subtypes of glioma." (PMID 32695001, 2020). "One study used SOX2 as a glioma-specific antigen for T-cell immunotherapy of glioma patients, given that SOX2 is overexpressed in glioma cells and tumor tissues." (PMID 32728033, 2020). "Another ES gene, SRY-box transcription factor 2 (SOX2), is associated with brain cancers and maintenance of CSC, specifically, in GBM and pediatric brain tumors, including glioma." (PMID 33137926, 2020). "Immunofluorescent staining confirmed that WISP1 was preferentially expressed in glioma cells expressing the GSC markers SOX2 and OLIG2, and was enriched in the proximity of GSCs." (PMID 32541784, 2020). "For example, lncRNA NEAT1 drove the development of glioma through inhibiting miR-132 to enhance the expression of SOX2." (PMID 32009853, 2020). "Overall, our findings illustrate that ASCL1, OLIG2, and SOX2 are coexpressed in tumor cells of both early and terminal tumors of the glioma mouse model in vivo, and tumor cells maintain a molecular identity reminiscent of that of OPCs." (PMID 32573857, 2020). "Actually, among several features determining the aggressiveness of gliomas, the expression of specific stemness genes, such as SOX2 and Oct4, correlates with a poor prognosis." (PMID 33081024, 2020). "This includes testicular germ cell tumors, as well as various carcinomas and gliomas/glioblastomas, that match SOX2’s lineage commitment." (PMID 32664542, 2020). "In glioma, proteins such as Sox2, Bmi1, hairy and enhancer split (Hes) play crucial roles in neural development and promote self-renewal and proliferation in glioma." (PMID 31992303, 2020). "In patients with grade III in primary gliomas and developed into glioblastoma in recurrent gliomas, 1 cases (1/6, 16.7%) with SOX2 expression decreased and 5 cases (5/6, 83.3%) were stable." (PMID 31718604, 2019). "OCT4 expression was shown to correlate with DNMT1 and DNMT3b expression in primary glioblastoma neurosphere, and the transgenic OCT4/SOX2 co-expression is able to increase the expressions of DNMTs in gliomas." (PMID 31771617, 2019). "To study the link between SIX1 and SOX2 in glioma, we used the cell lines U251 and GNS16626, representative of differentiated and stem-like phenotypes respectively." (PMID 30723235, 2019). "H&E staining confirmed the glioma origin of tumors, and IHC showed that the tumors derived from NADHhigh cells exhibited higher Ki-67 and Sox2 expression than those derived from NADHlow cells." (PMID 31747975, 2019). "Compared with primary gliomas, the overall expression of SOX2 decreased in adjuvant group (p = 0.003), but such tendency was largely not seen in non-adjuvant group (p = 0.317)." (PMID 31718604, 2019). "Our study provides precious knowledge about SOX2 status in the recurrent gliomas, which further enrich our understanding to glioma." (PMID 31718604, 2019). "Compared with primary high grade tumors, SOX2 expression increased in their paired recurrent gliomas in 0 cases (0.0%), while 13 cases (54.2%) decreased, 11 cases (45.8%) did not change." (PMID 31718604, 2019).
glioma (continued). "For instance, tunicamycin, an inhibitor of N-linked glycosylation which acts as an endoplasmic reticulum stress inducer, was shown to cause cell cycle arrest in G1 phase, blocking the self-renewal capability of glioma CSCs by reducing the expression of SOX2." (PMID 31683669, 2019). "Patients with SOX2 high expression in primary glioma had a longer median PFS than those with SOX2 low expression with marginal statistic significance (12.7 vs. 5.4 months, p = 0.083)." (PMID 31718604, 2019). "SOX2 high expression is common in brain HGG, a tendency of decreased SOX2 expression in recurrent gliomas was evidenced." (PMID 31718604, 2019). "Both TMZ and AP-2α synergistically inhibited the growth and induced the apoptosis of glioma cells, accompanied by decreased levels of Bcl-2, Pro Caspase-3 and the stem cell markers Nanog and Sox2 in a dose-dependent manner." (PMID 31534499, 2019). "Compared to NADHlow subpopulation, NADHhigh glioma cells highly expressed stem-related genes Nanog, Oct-4, Oligo2, and Sox2 at both mRNA and protein levels in GBM1 and LN229 cells." (PMID 31747975, 2019). "In line with our observations, inspection of datasets from the TCGA collection reveals a significant correlation between SIX1 and SOX2 expression in different tumor types, including glioma, soft-tissue sarcoma, prostate and esophageal cancer." (PMID 30723235, 2019). "Patients with low SOX2 expression in primary HGG usually have poorer prognosis, those with SOX2 expression decreased in recurrent glioma had worse outcome." (PMID 31718604, 2019). "For the first time, we presented that SOX2 expression decreased in recurrent glioma as compared to the corresponding primary glioma." (PMID 31718604, 2019). "In patients with grade III in primary and paired recurrent gliomas, 2 cases with SOX2 expression decreased (2/5, 40.0%) with SOX2 expression decreased, 3 cases (3/5, 60.0%) were stable." (PMID 31718604, 2019). "For the small sample size to analyze the prognostic value of SOX2, we further searched The Cancer Genome Atlas (TCGA) database and found SOX2 mRNA expression in 153 glioma cases." (PMID 31718604, 2019). "Previously, we detected that glioma cells possess the abnormal expression of genes, involved in maintenance of stem cell state, including SOX2." (PMID 30730955, 2019). "In patients with glioblastoma in primary and paired recurrent gliomas, 10 cases (10/11, 90.9%) with SOX2 expression decreased, 1 cases (1/11, 9.1%) were stable." (PMID 31718604, 2019). "The glioma stem-like cells are generally believed to express stemness and self-renewal markers, such as Sox2 and Nestin." (PMID 31027305, 2019). "The change in m6A modification and the transcript level of four glioma reprogramming factors (SOX2, SALL2, OLIG2 and POU3F2) and selected transcripts were validated by m6A RIP-PCR and RT-qPCR." (PMID 30781903, 2019). "Since SOX2 is a master regulator of stemness in stem-like glioma cells, the effect of RA on SOX2 expression has been determined." (PMID 31590252, 2019). "Low levels of AP-2α were primarily observed in glioma tissues with high expression of Nanog (Fisher's exact test, P<0.001), Sox2 (Fisher's exact test, P<0.001) and CD133 (Fisher's exact test, P<0.001)." (PMID 31534499, 2019). "Up-regulation of cathepsin B and uPA receptors induces SOX2 and Bmi1 expression, both critical for maintaining the stemness of glioma CSCs, while knockdown of cathepsin B and uPA receptors suppresses expression of SOX2, Bmi1 and nestin, in vivo." (PMID 31683669, 2019). "SOX2 is shown to be crucial in maintaining plasticity for bidirectional conversion between cancer stem-like and differentiated glioma cells in patient-derived mouse xenografts." (PMID 31683669, 2019). "We found that the expression of Nanog, Oct-4 and Sox2 was higher in fusion cells as compared to the parental glioma cells by RT-PCR." (PMID 31864321, 2019).
glioma (continued). "Sox2 and Nestin are enriched in glioma stem-like cells and maintain the cells’ stemness property and continued tumorigenicity." (PMID 31027305, 2019). "Patients were grouped into SOX2 high expression group (2+ and 3+, n = 21) and SOX2 low expression group (0+ and 1+, n = 3) according to the expression of SOX2 in primary gliomas." (PMID 31718604, 2019). "As previous reports have shown that BMP signaling directs astroglial differentiation in GSCs36–38, we expected that pSmad2-positive glioma cells would be enriched in stem cell markers, such as Sox2 and nestin, compared to pSmad1-positive glioma cells." (PMID 31602000, 2019). "Ectopic Sox2 expression is reported to induce invasion and migration of glioma cells, and was further confirmed by knockdown experiments." (PMID 31358880, 2019). "lncRNA NEAT1 inhibits cell invasion by targeting miR-132 to modulate SOX2 expression in glioma cells." (PMID 31631065, 2019). "This study was designed to investigate the role of lncRNA NEAT1, miR-132 and SOX2 interaction in glioma." (PMID 30053878, 2018). "As an oncogene, lncRNA NEAT1 played a role in glioma by targeting miR-132 and then indirectly promoting SOX2 expression." (PMID 30053878, 2018). "Although we identified the promotive function of NEAT1 in glioma and investigated its relationship with miR-132 and SOX2, the limitations should be pointed out and made up in the future." (PMID 30053878, 2018). "In terms of common molecular signatures, both NSCs and glioma CSCs exhibit Y-box binding protein 1 (YB-1), Sox-2, Nestin and Msi1 expression which are lost upon differentiation." (PMID 30510501, 2018). "Among these pluripotent transcription factors overexpressed in high-grade gliomas are “sex-determining region Y-Box (SOX2), octamer-binding transcription factor 4 (OCT 4), and Nanog homeobox (NANOG)”." (PMID 29849920, 2018). "SOX2 expression was up-regulated in glioma tissues, and the elevated level was positively related to the progression of glioma." (PMID 30053878, 2018). "In four glioma cell lines (U87, U251, SHG44, U-118 MG), the expression of NEAT1 and SOX2 was distinctively elevated compared with normal cell line HA, whereas miR-132 expression in glioma cell lines was significantly lower than that in HA cell line." (PMID 30053878, 2018). "Based on our previous findings that Bcl11b-KD reduced the expression of stemness-related genes (Sox2 and Bmi1) in glioma cells, we also examined the expression of stemness-related genes in the scramble and Bcl11b-KD cultures." (PMID 29416501, 2018). "Meanwhile, miR‐129 directly targeted at SOX2 and suppressed cell viability and proliferation of glioma stem cells by suppressing SOX2 expression." (PMID 29808528, 2018). "NEAT1 negatively regulated the expression of miR-132 in glioma while miR-132 targeted SOX2 to down-regulate its expression." (PMID 30053878, 2018). "The down‐regulation of MALAT1 and miR‐129 overexpression both suppressed glioma tumour growth via SOX2 expression promotion in vivo." (PMID 29808528, 2018). "We also found that SOX2, a glioma reprogramming factor, as the METTL3 target in promoting glioma stem cell growth." (PMID 29460395, 2018). "To further validate this finding, we performed quantitative immunohistochemical analysis of SOX2 expression in a larger cohort of 40 surgical specimens from high-grade gliomas." (PMID 30041684, 2018). "Immunostaining analysis of primary glioblastoma samples showed that cells overexpressing ALKB5 are characterized by the expression of the glioma stem cell markers SOX2, Nanog, Nestin, and OCT4; this stem cell phenotype is rescued by ALKBH5 expression." (PMID 30279357, 2018). "SOX2, one of the glioma reprogramming factors, was methylated in its specific sites of mRNA 3′ UTR by METTL3." (PMID 30149601, 2018). "MALAT1 enhanced glioma stem cell viability and proliferation abilities and promoted glioma tumorigenesis through suppressing miR‐129 and facilitating SOX2 expressions." (PMID 29808528, 2018).